RELA (RELA proto-oncogene, NF-kB subunit)
Diseases named in the same sentence as RELA in open-access papers (continued):
Sharing a sentence is not in itself a finding about the gene and the disease.
viral infection (21 papers, 2009 to 2026). "We were therefore surprised to discover that cells from mice genetically deficient in key NF-κB subunits (such as RelA, c-Rel, or p50) were mostly normal in their ability to activate ifnβ expression after virus infection." (PMID 22022260, 2011). "Our study revealed that as viral infection progresses, despite all three time series remaining active, the transcription of RELA gradually decreases." (PMID 38673764, 2024). "Enriched KEGG and Reactome terms include genes involved in IFN signaling, viral infection, and adaptive immunity, while there were several enriched transcription factor motifs, including Stat2, IRFs, and RelA." (PMID 35578269, 2022). "The map illustrates that HSPA8 and proteins in subnetworks, such as EIF2AK3, TLR4, NFKB1, BAK1, and RelA, are enriched in viral infection of several viruses." (PMID 34769416, 2021). "During the process of viral infection, NF-κB RelA traffics to the nucleus and interacts with BRD4, CDK9 and other components of the positive transcription elongation factor (p-TEFb)." (PMID 33799525, 2021). "RelA/p65 is a member of the NF-kB family, which normally induces antiviral interferon responses upon virus infections but also in the early stage of the infection, and stimulates HCMV major immediate early promoter (MIEP) to enhance HCMV replication." (PMID 35004357, 2021). "Transcriptome analysis of lnc-EPAV-silenced macrophages showed that lnc-EPAV was critical for induction of NF-κB/RELA target genes during viral infection." (PMID 31363026, 2019). "RelA/NFkB dependent increase in the expression of miR-146a is shown earlier by several investigators in Alzheimer's disease (AD), viral infection, epilepsy and prion disease." (PMID 21887328, 2011). "In contrast, in vivo experiments showed that RelA deficiency did not affect the CD8+ T-cell response to acute viral infection or transplanted tumors." (PMID 38504985, 2024). "The canonical NF-κB pathway, triggered by microbial and viral infections, allow to dimers formation containing RelA (also known as p65), c-Rel, or p50 proteins, which are normally retained in the cytoplasm by inhibitors of κB proteins (IκBα, IκBβ, IκBε, IκBγ and Bcl-3)." (PMID 30914680, 2019). "However, RelA-deficient and p50-deficient MEFs can produce IFN-α after viral infection, whereas only early IFN-I transcription is reduced." (PMID 29142134, 2018). "The qRT-PCR results indicated an up-regulation trend for DDX58, STAT1, and MX1, while IRAK1, MAPK11, RELA, and ICAM1 exhibited a down-regulation trend as the duration of the viral infection increased." (PMID 38673764, 2024). "Under viral infection conditions, lnc-EPAV competitively binds SFPQ, which dissociates SFPQ from the RELA promoter and promotes RELA expression." (PMID 39408810, 2024). "We identified EP300, MOV10, RELA, and TRIM25 as top candidates, and more than 60 additional proteins involved in the epigenetic response during viral infection that has therapeutic potential." (PMID 34031419, 2021). "Given that TRAF6 RING finger is required for NF-κB activation, this observation is consistent with previous reports showing that lack of p50, Rel, RelA or IKKβ barely affected type I IFN production in response to viral infection." (PMID 19479062, 2009). "Analyzing the results, we noted that RelB, a member of NF‐κB protein family, was significantly downregulated by PFV infection, while other four members of the family, such as relA, c‐rel, p50, and p52, did not detect significant changes in transcriptional level 24 h after virus infection." (PMID 32881382, 2020). "While an overexpression effect cannot be ruled out, it is of note that RELA maintains constitutive expression of IFN-β and a subset of ISGs in the absence of viral infection." (PMID 41171864, 2025).
colon carcinoma (18 papers, 2013 to 2025). "We found that all levels of phosphorylated ERK (p-ERK), p-AKT, and p-RelA were lower in TMEM211-silenced colon cancer cells compared to those in scramble cells, especially in DLD-1 cells." (PMID 37367036, 2023). "Levels of phosphorylated ERK, AKT and RelA (NF-κB p65) were also decreased in TMEM211-silenced colon cancer cells." (PMID 37367036, 2023). "A sesquiterpene lactone named helenalin was reported to trigger autophagy via inhibition of RELA/NF-κB p65 expression in the RKO colon carcinoma, MCF-7 breast adenocarcinoma and A2780 human ovarian cancer cell lines." (PMID 36497321, 2022). "To verify the expression of RelA in colon cancer tissue, we conducted immunohistochemical analyses in average, paracancer, and colon cancer tissue samples from the patients." (PMID 34867383, 2021). "Kaempferol inhibits the expression of RelA, a crucial molecule in the NF-κB pathway, thereby promoting the apoptosis of colon cancer cells and inhibiting tumor growth." (PMID 34867383, 2021). "To investigate the possible connection of p68 with RelA, we conducted immunohistochemical (IHC) analysis in normal and colon carcinoma tissue samples procured from Indian patients." (PMID 31351496, 2019). "A strong positive correlation was perceived between the abundance of p68 and RelA in both normal and colon carcinoma tissue samples." (PMID 31351496, 2019). "Strong positive correlation was observed between the abundance of β-catenin, TCF4 and RelA in both normal and colon carcinoma tissue samples." (PMID 31351496, 2019). "p68, β-catenin and RelA proteins were found to bear strong positive correlation in normal and colon carcinoma patient samples." (PMID 31351496, 2019). "The expression of p68 and RelA exhibited marked elevation in colon carcinoma samples compared to that of normal." (PMID 31351496, 2019). "In this study, we revealed compelling evidences of p68 mediated RelA gene regulation and subsequent activation of NF-κB signaling axis in colon cancer." (PMID 31351496, 2019). "Collectively, these results suggest MIIP-S303 phosphorylation maintains RelA Ac-K310 levels in colon cancer cells in vivo through its antagonistic effects on HDAC6, thus facilitates tumor metastasis." (PMID 29038521, 2017). "Therefore, we can demonstrate that kaempferol, the bioactive component of PM, can promote the apoptosis of colon cancer cells by inhibiting RelA, thus playing a role in treating cancer." (PMID 34867383, 2021). "The feasibility of PM in the treatment of human CRC from the perspective of morphology and protein expression was further proven, by verifying that the expression of RelA in human colon cancer tissues was indeed higher than that in normal tissues and paracancer tissues." (PMID 34867383, 2021). "The results showed that kaempferol could inhibit the expression of RelA in colon cancer cell HCT116." (PMID 34867383, 2021). "Indeed, the inhibition of RelA expression with RelA siRNA enhanced in vitro and in vivo colon cancer cell responses to irinotecan." (PMID 31952106, 2020). "Hence, to investigate the possible connection of β-catenin with RelA, we conducted immunohistochemical (IHC) analysis in normal and colon carcinoma tissue samples procured from Indian patients." (PMID 31351496, 2019). "Increased RelA expression in colon carcinoma samples has been substantiated by several studies." (PMID 31351496, 2019). "RelA protein and mRNA levels were enhanced by p68 in colon cancer cells." (PMID 31351496, 2019). "In Nlrp12−/− mice, robust p52 generation in stromal cells through the non-canonical pathway led to colon cancer associated inflammation, a hallmark for aberrant RelA activity." (PMID 25905673, 2015). "Therefore, we stimulated 2D cultured MC-38 colon cancer cells with LPS and analyzed p65/RelA subcellular localization by immunofluorescence and by immunoblotting of nuclear extracts." (PMID 25978030, 2015).
colon carcinoma (continued). "According to a recent study on colon cancer, YTHDF1 can promote the translation of RELA, participate in the NF‐κB pathway, and promote tumor development." (PMID 39821576, 2025). "We found that MC-38 mouse colon cancer cells contain functional hypoxic (HIF-1α) and inflammatory (p65/RelA) signaling pathways." (PMID 25978030, 2015). "Moreover, after treating colon cancer cell HCT116 at concentrations of 60, 90, and 120 μM for 24 h by kaempferol, the expressions of RelA and apoptosis-related proteins Bax and Bcl2 were detected by WB." (PMID 34867383, 2021). "However, in contrast to LPS treatment, exposure of MC-38 colon carcinoma cells to hypoxia for 0.5 to 4 hours did not induce nuclear translocation of p65/RelA as shown by immunofluorescence and immunoblotting of nuclear extracts, although HIF-1α proteins levels were stabilized under these conditions." (PMID 25978030, 2015).
hepatocellular carcinoma (18 papers, 2008 to 2025). A malignant tumor that arises from hepatocytes. "Taken together, these results demonstrate that the T505A mutation results in a more tumour-promoting form of RelA that leads to the earlier onset of more aggressive hepatocellular carcinoma." (PMID 26853469, 2016). "Low HNF4-α expression has been associated with worst prognosis of hepatocellular carcinoma (HCC) through a robust activation of RELA, whereas higher HNF4-α expression inhibited NF-κB expression and improved HCC outcome." (PMID 27192147, 2016). "Our study demonstrated that treatment of tumor-bearing mouse models of hepatocellular carcinoma with different TKIs such as apatinib, lenvatinib, and regorafenib resulted in increased activation of RelA signaling in glomerular endothelial cells and podocytes." (PMID 36744132, 2023). "Nonetheless, we have established for the first time in vivo the importance of the RelA Thr505 motif for both chemical and surgically induced liver regeneration together with carcinogen-induced hepatocellular carcinoma." (PMID 26853469, 2016). "Moreover, not only did we observe earlier onset of cancer in this study but tumours in RelA T505A mice were more malignant hepatocellular carcinomas compared with the adenomas predominantly seen in control mice at this time point." (PMID 36240065, 2022). "Indeed, in our first report using the RelA T505A mouse with the DEN model of hepatocellular carcinoma, this was what we observed." (PMID 36240065, 2022). "Interestingly, while the numbers of adenomas are broadly equivalent between the two mice strains (16 foci from 13 WT mice, 12 foci from 12 RelA T505A mice), the hepatocellular carcinoma numbers were dramatically different." (PMID 26853469, 2016). "In this study, RBM23 did not affect the activation and expression of IkBa in our study; unexpectedly, we found that RBM23 could improve the level of RelA/p65 mRNA, thereby increasing the activity of the NF-κB signaling pathway to promote the angiogenesis of hepatocellular carcinoma." (PMID 33791378, 2021). "In models of hepatitis B virus–related hepatocellular carcinoma and in sarcoma cell lines, classical NFKB signaling (RELA) controls metabolic substrate preference in favor of glycolysis through transcriptional upregulation of HK2." (PMID 38272231, 2024). "We enriched the common target genes in the GO pathway and KEGG pathway and found that AKT1, RELA, and JUN are likely to be potential therapeutic targets for hepatocellular carcinoma." (PMID 36874613, 2023). "In summary, this study demonstrates that RBM23 regulates the activity of the NF-κB signaling pathway in HCC via directly targeting RelA/p65; these data revealed the RBM23-RelA/p65-NF-κB axis as a mechanism of promoting the angiogenesis in hepatocellular carcinoma." (PMID 33791378, 2021). "This major cleavage site of p65/RelA has been previously reported in HeLa and SK-Hep1 hepatoma cells but not in human PBLs." (PMID 19046417, 2008). "Firstly, we analyzed the relationship between RELA or DPAGT1 expression and the prognosis of HCC patients using The Cancer Genome Atlas Liver Hepatocellular Carcinoma (TCGA‐LIHC) database." (PMID 40919676, 2025).
hepatocellular carcinoma (continued). "The results showed that wogonin and baicalein, the main chemical components of SB, could inhibit the viability and proliferation of hepatocellular carcinoma cells, promote apoptosis through the mitochondrial apoptotic pathway, and effectively act on AKT1, RELA, and JUN targets." (PMID 36874613, 2023).
brain tumor (14 papers, 2016 to 2024). "With the presence of C11orf95 and RELA preserved functional domains in the different RELAFUS variants, expression of RELAFUS2-4 induced brain tumor formation." (PMID 33228790, 2020). "Analysis of brain tumor (n = 5) and stroma (n = 4) identified increased RELA expression in stroma as compared to tumor compartments in the Albino brain oncomine dataset." (PMID 29062041, 2017). "In this investigation, a comparative study of the mRNA expression of NF-κB p65 (RelA) and TNFα in both 33 brain tumor samples and TCGA datasets has revealed that the transcriptional activity of these genes is significantly higher in tumor samples than in normal samples." (PMID 37892820, 2023). "Our findings suggest that RELAFUS1 might induce brain tumor formation through two main oncogenic pathways regulated by C11orf95 and RELA target genes." (PMID 33685520, 2021). "To identify tumor-specific candidate regulatory elements we performed pairwise comparisons between three different mouse brain tumors (YAP1-, PDGFB- and RELA-driven tumors) and normal mouse brains." (PMID 37739938, 2023). "Both H3K27ac and RNAPII-Ser2,5p FFPE-CUTAC on RELA- and PDGFB-driven brain tumors showed much better sensitivity based on number of peaks called and much higher FRiP values than either H3K27ac CUT&Tag on frozen kidney or FACT-seq on FFPEs." (PMID 37739938, 2023).
atherosclerosis (13 papers, 2018 to 2026). A disease characterized by the build-up of fatty material and calcium deposition in the arterial wall resulting in partial or complete occlusion of the arterial lumen. "For instance, we observed enhanced adipogenesis and osteogenesis in RelA−/− MSCs, which suggests that RelA deficiency may cause atherosclerosis-associated abnormal lipid accumulation and vascular ossification." (PMID 29968158, 2018). "Seven core targets-IFNG, CXCL8, TNF, TGFB1, IL2, IL4, and RELA-were identified via network pharmacology, involving key pathways such as lipid-atherosclerosis, AGE-RAGE, and IL-17 signaling." (PMID 40708520, 2026). "The present study has demonstrated the role of PARP in modulating inflammatory responses through assembly/disassembly of NF-κB subunits (IκBα with either RelA/p50 or RelB/p52) in monocytes/macrophages, major participants in the pathogenesis of atherosclerosis." (PMID 38335214, 2024). "Furthermore, epigenetic changes were also identified in several genes including RELA (RELA Proto-Oncogene, NF-KB Subunit), NOS3 (Nitric Oxide Synthase 3), KLF4 (KLF Transcription Factor 4) and APOE (Apolipoprotein E) that have been linked to progression of atherosclerosis." (PMID 37190071, 2023). "Firstly, we demonstrated that RSV might inhibit ferroptosis to exert anti‐atherosclerosis effect; In addition, RSV regulates ferroptosis mainly through six biomarkers, including IL1B, RELA, HIF1A, SRC, PTEN, and MAPK1, in AS treatment." (PMID 40697701, 2025). "Moreover, our study constructed miRNA-mRNA and TF-mRNA regulatory networks, finding that regulators such as hsa-miR-203a-3p, RELA, and NFKB1 play core roles in this network, further supporting the complex molecular interactions between gout and atherosclerosis." (PMID 39677038, 2024).